FBXW5 (F-box and WD repeat domain containing 5)
Description:
Substrate recognition component of both SCF (SKP1-CUL1-F-box protein) and DCX (DDB1-CUL4-X-box) E3 ubiquitin-protein ligase complexes. Substrate recognition component of the SCF(FBXW5) E3 ubiquitin-protein ligase complex which mediates the ubiquitination and subsequent proteasomal degradation of SASS6 during S phase, leading to prevent centriole reduplication. The SCF(FBXW5) complex also mediates ubiquitination and degradation of actin-regulator EPS8 during G2 phase, leading to the transient degradation of EPS8 and subsequent cell shape changes required to allow mitotic progression. Substrate-specific adapter of the DCX(FBXW5) E3 ubiquitin-protein ligase complex which mediates the polyubiquitination and subsequent degradation of TSC2. May also act as a negative regulator of MAP3K7/TAK1 signaling in the interleukin-1B (IL1B) signaling pathway.
Synonyms: FBW5; DKFZP434B205; MGC20962
Tractability: PROTAC: UniProt records ubiquitination sites on it; ubiquitination databases record sites on it.
Gene: Protein-coding gene on chromosome 9 (136,940,435 to 136,944,762, reverse strand). Ensembl gene ENSG00000159069.
Subcellular location: Cytoplasm
Subcellular location (Human Protein Atlas): Mitochondria
Pathways (Reactome):
Metabolism of proteins: Association of TriC/CCT with target proteins during biosynthesis; Neddylation
Immune System: Antigen processing: Ubiquitination & Proteasome degradation
Gene Ontology:
Molecular function: protein binding; protein kinase binding
Biological process: proteasome-mediated ubiquitin-dependent protein catabolic process; protein ubiquitination; regulation of centrosome duplication; SCF-dependent proteasomal ubiquitin-dependent protein catabolic process; centrosome duplication; cilium assembly; regulation of cell cycle process; regulation of mitotic nuclear division
Cellular component: Cul4-RING E3 ubiquitin ligase complex; cytoplasm; SCF ubiquitin ligase complex; cytosol
Genetic constraint (gnomAD): Loss-of-function variants: 74 observed, 47.83 expected, observed/expected ratio (o/e) 1.55, 90% interval 1.28 to 1.86. The synonymous counts are far from expectation, so gnomAD's model fits this gene poorly and the ratio says little. Missense variants: 1,049 observed, 769.18 expected, observed/expected ratio (o/e) 1.36, 90% interval 1.3 to 1.43. Synonymous variants: 517 observed, 342.02 expected, observed/expected ratio (o/e) 1.51, 90% interval 1.41 to 1.63.
Homologues: Orthologues: chimpanzee FBXW5 (99% identical), macaque FBXW5 (97% identical), guinea pig FBXW5 (92% identical), dog FBXW5 (91% identical), rat Fbxw5 (90% identical), mouse Fbxw5 (90% identical), pig FBXW5 (90% identical), zebrafish fbxw5 (69% identical), tropical clawed frog fbxw5 (52% identical), Drosophila melanogaster Fbw5 (43% identical). Paralogues in human: FBXO15 (13% identical).
Diseases named in the same sentence as FBXW5 in open-access papers:
FBXW5 is named in the same sentence as 18 diseases in open-access papers, as found by Europe PMC text mining. Sharing a sentence is not in itself a finding about the gene and the disease. The quoted sentences say what the papers report.
Parkinson disease (3 papers, 2015 to 2022). A progressive degenerative disorder of the central nervous system characterized by loss of dopamine producing neurons in the substantia nigra and the presence of Lewy bodies in the substantia nigra and locus coeruleus. "Previous work has shown that TIPE1/Oxi-beta can competitively bind to FBXW5 with tuberous sclerosis complex 2 (TSC2), increasing the stability of TSC2 and promoting excessive autophagy in Parkinson’s disease." (PMID 36118167, 2022). "In a Parkinson’s disease model, TIPE1 binds to FBXW5, increasing autophagy through activation of TSC2." (PMID 29108244, 2017).
cardiac hypertrophy (2 papers, 2023 to 2024). "Fbxw5 deficiency aggravated cardiac hypertrophy, while adeno-associated virus 9-mediated overexpression of Fbxw5 protected mice from hypertrophic stimuli, which is in line with our screening result for Fbxw5." (PMID 36969608, 2023). "FBXW5 negatively regulates pathological cardiac hypertrophy by inhibiting the TAK1 signaling pathway." (PMID 38615011, 2024). "Recently, Fbxw5 was shown to act as a negative regulator of pathological cardiac hypertrophy." (PMID 36969608, 2023).
gastric cancer (2 papers, 2019 to 2022). A primary or metastatic malignant neoplasm involving the stomach. "The present study investigates the role of FBXW5 in tumorigenesis and metastasis, as well as the regulation of key signaling pathways in gastric cancer; using in-vitro FBXW5 knockdown/overexpression cell line and in-vivo models." (PMID 31213005, 2019). "Our study demonstrates a novel oncogenic role of FBXW5 in gastric cancer and draws further interest regarding its clinical utility as a potential prognostic biomarker and therapeutic target." (PMID 31213005, 2019). "Collectively, these analyses substantiated the role of FBXW5 in gastric cancer metastasis as elucidated from in-vitro and in-vivo studies." (PMID 31213005, 2019). "Nevertheless, our findings underscore a contributory role of FBXW5 to an aggressive tumor phenotype in gastric cancer and warrant further validation regarding its potential as a therapeutic strategy." (PMID 31213005, 2019). "FBXW5 expression was knocked down in MKN1 cells using FBXW5 targeted siRNAs to investigate the role of FBXW5 in gastric cancer cell proliferation." (PMID 31213005, 2019). "When considered together, our study identifies the novel oncogenic role of FBXW5 in gastric cancer and draws further interest regarding its clinical utility as a potential therapeutic target." (PMID 31213005, 2019). "When considered together, our findings confirmed the tumorigenic potential of FBXW5 in gastric cancer and support a previous observation in NSCLC that suggested the role of FBXW5 in promoting cell proliferation and tumor growth." (PMID 31213005, 2019). "In conclusion, the current study provides a detailed characterization of the oncogenic potential of FBXW5 in gastric cancer." (PMID 31213005, 2019). "Furthermore, GSEA analyses carried out between low and high FBXW5 samples supported the pro-metastatic role of FBXW5 as high FBXW5 samples were found to be enriched in gene sets related to metastasis, RhoA signaling and advanced stage gastric cancer." (PMID 31213005, 2019). "In addition to confirming the tumorigenic role of FBXW5, our study identified a novel pro-metastatic role of FBXW5 in gastric cancer." (PMID 31213005, 2019). "Our findings fall in line with the previous observation, and further, suggest that down regulation of RhoA-ROCK1 and FAK activation in FBXW5 depleted cells could together contribute to the decrease in focal adhesions and migratory characteristics of gastric cancer cells." (PMID 31213005, 2019). "Four gastric cancer cell lines, MKN1, CLS145, AGS and SNU1, were shown to have varying levels of FBXW5 mRNA and protein expressions." (PMID 31213005, 2019). "The current study provides a novel insight into FBXW5-induced tumorigenesis and metastasis mediated via the FAK-Src signaling pathway in gastric cancer." (PMID 31213005, 2019). "Despite its known function as a component of the Skp1-Cullin-F-box (SCF) ubiquitin ligase complex, the role of FBXW5 in gastric cancer tumorigenesis and metastasis has not been investigated." (PMID 31213005, 2019). "Since c-Myc degradation is also regulated by F-box/WD repeat-containing protein 7 (FBXW7), a widely studied F-box member with known tumor suppressor functions, we determined the correlation between FBXW5 and FBXW7 expressions in gastric cancer, both in-vivo and in-vitro." (PMID 31213005, 2019).
lung carcinoma (2 papers, 2020 to 2022). "FBXW5 mRNA was broadly detectable in common human malignant cancers, including GC, colorectal cancer, and lung cancer." (PMID 35210431, 2022). "However, in a set of lung cancer cells, the complex responsible for degrading DLC-1 comprises CULT4, DDB1 and FBXW5 E3 ligases all together, thus suggesting the difference existing in the composition of E3 ligases between cancer cells and hMSCs." (PMID 33148199, 2020).
non-small cell lung carcinoma (2 papers, 2022). A group of at least three distinct histological types of lung cancer, including non-small cell squamous cell carcinoma, adenocarcinoma, and large cell carcinoma. "Previously, FBXW5 was proposed to form a complex with CUL4A in non-small cell lung cancer, which led to the degradation of the tumor suppressor protein, DLC1, a Rho GTPase-activating protein, ultimately promoting cell proliferation." (PMID 35210431, 2022).
chondrosarcoma (1 paper, 2019). A malignant cartilaginous matrix-producing mesenchymal neoplasm arising from the bone and soft tissue. "Among them, a SNV in F-Box and WD Repeat Domain Containing 5 (FBXW5) is the only variation previously reported in COSMIC in tumor types different to chondrosarcoma." (PMID 30987403, 2019).
gastric tumor (1 paper, 2022). "In this study, clinical gastric tumor samples, cell-based experiments, and nude mouse models were employed to provide the first evidence that FBXW5 binds to and degrades LATS1 through the ubiquitin-proteasome pathway, ultimately inactivating the Hippo signaling pathway." (PMID 35210431, 2022).
glioma (1 paper, 2022). A benign or malignant brain and spinal cord tumor that arises from glial cells (astrocytes, oligodendrocytes, ependymal cells). "In addition, by retrieving the immunohistochemistry (IHC) staining dataset from the Human Protein Atlas database, we found that the FBXW5 protein is expressed in most of the common human cancers, except lymphoma and glioma." (PMID 35210431, 2022).
lymph node metastasis (1 paper, 2022). "A high expression of FBXW5 was found to be associated with lymph node metastasis (p < 0.001), poor TNM stage (p = 0.018), and low differentiation (p = 0.042)." (PMID 35210431, 2022).
tumor (6 papers, 2018 to 2025). "Based on our results, a high level of FBXW5 underlies tumor invasion, lymph node metastasis, TNM stage, and poor prognosis in GC patients." (PMID 35210431, 2022). "Based on mouse xenograft assays, FBXW5 silencing attenuated the growth of subcutaneous tumor xenografts." (PMID 35210431, 2022). "We validated the function of the FBXW5 protein in vivo by constructing a subcutaneous xenograft tumor model in nude mice." (PMID 35210431, 2022). "Overexpression of FBXW5 promotes in-vivo tumor growth, whereas its inhibition down regulates in-vivo tumor metastasis." (PMID 31213005, 2019). "Conversely, overexpression of FBXW5 significantly promoted in-vitro cell proliferation and in-vivo tumor growth." (PMID 31213005, 2019). "Consistently, knockout of FBXW5 significantly down regulated in-vivo tumor metastasis." (PMID 31213005, 2019). "Similarly, the role of FBXW5 in cell migration as elucidated from in-vitro studies was further substantiated by a knockout model of FBXW5, which demonstrated a significant down regulation in tumor metastasis to the liver." (PMID 31213005, 2019). "However, another FBXW protein, FBXW5, exerts a tumor-promoting effect in GC." (PMID 40721413, 2025). "Further, IHC staining of the xenograft tumor tissue revealed that CD31, vimentin, N-cadherin, and Ki-67 were repressed when FBXW5 was depleted." (PMID 35210431, 2022). "Collectively, the silencing of FBXW5 may reduce the entry of YAP1 into the nucleus and inhibit the growth of tumor xenografts." (PMID 35210431, 2022). "FBXW5 was reported to interact with cullin 4A–RING ubiquitin ligase–DNA damage-binding protein 1 (CUL4A–DDB1) and act as a major substrate recognition component for the ubiquitination and degradation of deleted in liver cancer 1 (DLC1), which promotes tumor progression." (PMID 35210431, 2022).
cancer (5 papers, 2018 to 2022). A tumor composed of atypical neoplastic, often pleomorphic cells that invade other tissues. "By searching the Human Protein Atlas Image Classification database, we found that FBXW5 is broadly expressed in human cancers, including GC." (PMID 35210431, 2022). "Interestingly, a mutation at the SEC23B S186 site, a cancer-related mutation occurring in human melanoma, could abolish the interaction between SEC23B and FBXW5, resulting in an increase in autophagy and promoting the survival of cancer cells." (PMID 31595159, 2019). "we further investigated that FBXW5 was highly expressed, FBXW10 and FBXW12 were lowly expressed, and other members were moderately expressed in pan-cancer." (PMID 36591289, 2022).
infection (1 paper, 2014). The state of being infected such as from the introduction of a foreign agent such as serum, vaccine, antigenic substance or organism. "Infection of shRNAs against eight F-box proteins (FBXL5, FBXW5, FBXO3, FBXO4, FBXO5, FBXO24, FBXO25 and FBXO27) upregulated Snail1 protein levels (at least by 2-fold) compared with parental cells or cells infected with a control shRNA." (PMID 24157836, 2014).
metabolic disorders (1 paper, 2025). "Hepatocyte-specific FBXW5 overexpression aggravated diet-induced metabolic disorders in the liver and activated ASK1-associated MAPK signaling in the liver, according to an in vivo study; however, hepatocyte-specific FBXW5 deficiency significantly inhibited the progression of these abnormalities." (PMID 40292292, 2025).
FBXW5 also shares sentences with these, for which no sentence is quoted: colorectal cancer (1 paper); Hepatic steatosis (1); intracerebral hemorrhage (1); lymphoma (1); myocardial ischemia (1).